SLC2A1 (solute carrier family 2 member 1)
Diseases named in the same sentence as SLC2A1 in open-access papers (continued):
Sharing a sentence is not in itself a finding about the gene and the disease.
cancer (continued). "We identified a robust upregulation of GLUT1 (SLC2A1), a key rate-limiting factor in the transport of glucose in cancer cells, and genes involved in central glucose metabolism (HK2, ENO1, PKM, and LDHA), PPP (G6PD), and de novo serine biosynthesis pathway (PSAT1, PSPH, and SHMT2)." (PMID 40371988, 2025). "In this study, we investigate the expression of SLC2A1 and MPST across various types of cancer." (PMID 40746529, 2025). "For a long time, it was thought that only SLC2A1 is responsible for the increased influx of glucose into cancer cells and that SLC2A3 may contribute to glucose uptake in cancer cells to some extent." (PMID 38339256, 2024). "The induction of GLUT transporters (SLC2A1/GLUT1 and SLC2A3) to support aerobic glycolysis (the Warburg effect) is well established, a phenomenon that is reinforced by HIF-1/2α transcriptional control in the hypoxic niche of malignant tumors." (PMID 38414005, 2024). "Moreover, we examined the protein expression levels of the four ARGs (PLK1, SLC2A1, ANGPTL4, CDKN3) in cancer tissues and para-cancer tissues from clinical LUAD patients." (PMID 38345559, 2024). "More importantly, there was also a remarkably positive correlation between SLC2A1 and PD-L1 or CTLA4 across cancers, which could reflect its prognosis and immunotherapy significance." (PMID 37833332, 2023). "In addition, SLC2A1 is positively correlated with the neutrophils and CAFs in the TME in most cancers." (PMID 36358765, 2022). "We found that high expression of SLC2A1 corresponds to low immune, stromal and ESTIMATE scores in the TME in most cancer types, which indicated that SLC2A1 might be mainly expressed by cancer cells." (PMID 36358765, 2022). "For example, SLC2A1 was significantly postively correlated with Th2 CD4+ T cells and significantly negtively correlated with CD 8 + T cell, M2 macrophages and B cell in a variety of cancers." (PMID 36712872, 2022). "Although the overexpression of SLC2A1 can further enhance glycolysis and cell proliferation in various cancers, a comprehensive pan-cancer analysis on SLC2A1 is lacking." (PMID 36358765, 2022). "We found that SLC2A1 was strongly or medium stained in most cancers, but was negative or weakly stained in most normal tissues." (PMID 36358765, 2022). "In this context, it is worth mentioning that cancer cells, including non-solid as well as solid malignancies, facilitate glucose uptake by the GLUT1 transporter, which is encoded by the SLC2A1 gene (solute carrier family 2 member 1)." (PMID 36230918, 2022). "In concordance with the dysregulation of SLC2/5 family carbohydrate transporters and regulatory miRNAs in cancer cells, some miRNAs have been demonstrated to govern the expression of SLC2/5 genes, in which the facilitative uniporter SLC2A1/GLUT1 is particularly well studied." (PMID 35755805, 2022). "High SLC2A1 expression was related to decreased TILs, CD8 T cells, B cells, TCR signaling and BCR signaling, whereas it was related to increased proliferation and cancer/testis antigen expression." (PMID 33735188, 2021). "SLC2A1 (also GLUT1) is a type of glucose transporter that is upregulated in many tumors, and plays an important role in maintaining the growth and reproduction of cancer cells." (PMID 33929972, 2021). "Hypoxia could activate multiple proglycolytic genes (SLC2A1, LDHA and PDK1) and glycolytic enzymes in favor of glucose uptake and glycolysis in both cancer cells and TILs, but depresses TCA cycle and aerobic oxidation." (PMID 34858835, 2021). "The microarray and RNAseq showed 15 SLC transporters being overexpressed when compared with the normal tissue; among them (apart from glucose transporter SLC2A1) lactate transporter SLC16A3 and SLC6A14, which was overexpressed at least 2-fold in cancer patients." (PMID 33195271, 2020).
cancer (continued). "Regarding the impact of macrophages and hypoxia on cancer cells, we found that despite the increased levels of glucose consumption and SLC2A1 expression, there was no increase of lactate production, despite the increase in LDHA expression and acidosis." (PMID 32231135, 2020). "In parallel, we examined the effects of ATGL on glycolysis: lower glucose uptake, extracellular lactate concentration, and decreased expression of SLC2A1/GLUT1 and SLC16A1/MCT1, the glucose and lactate transporters commonly found altered in different types of cancer, were remarked." (PMID 30367149, 2019). "The role of SLC2A1/GLUT1 and SLC2A3/ GLUT3 has been widely studied in cancers." (PMID 29876008, 2018). "SLC2A1 expression was elevated by 20.6-fold in pT1 and higher BC and by 7.7-fold in RPC compared to the non-BC control groups and other cancers, indicating that the overexpression of SLC2A1 is relatively specific to urothelial cancers." (PMID 30214686, 2018). "We found that SLC2A1, a target of miR-30c-2-3p, was downregulated in cells treated with cancer serum but not with normal serum." (PMID 29942793, 2018). "Glucose transporter 1 (GLUT1), also named facilitates glucose transporter member 1 (SLC2A1), has been demonstrated to be a pivotal rate-limiting element in the transport of glucose in malignancy cells and overexpressed in different types of human cancers." (PMID 28915636, 2017). "Furthermore, the expression of SLC2A1, CTNNB1, ACTB, and CLTC were significantly changed in only one type of cancer during migration." (PMID 28640862, 2017). "Another 6 genes, SUB1, SLC2A1, CTNNB1, ACTB, HSP90B1, and CLTC were selected from the remaining unknown migration-related genes in order to confirm their relationship with cancer cell migration." (PMID 28640862, 2017). "Importantly, MSH6, PTGS2, HDAC1, JUN, SLC2A1, and MMP1 were enriched in the pathway in cancer, of which MSH6 and MMP1 were candidate genes." (PMID 27034707, 2016). "However, the results showed that more advanced tumors (pT3-4, pN1-3) were more likely to be more frequently positive and to have a higher mean levels for both SLC2A1 and SLC2A3 transcripts than less advanced cancers (pT1-2, N0)." (PMID 25412955, 2015). "The study of gene copy number showed that the SLC2A1 gene amplification was found in 8.6% (6/70) of cancer cases, but in none normal tissue sample." (PMID 22270867, 2012). "Consequently, the ability of these cancer cells to downregulate IGSF3 and SLC2A1 to evade CAR cell killing might be limited, upgrading their potential for serving as future CAR targets in our minds." (PMID 37835579, 2023). "Notably, SLC2A1 is remarkably positively correlated with CD274 (PD-L1) and CTLA4 in most cancers." (PMID 36358765, 2022). "Studies on SLC2A1 in pan-cancer analysis were previously lacking." (PMID 36358765, 2022). "Notably, SLC2A1 was remarkably positively correlated with PD-L1 and CTLA4 in most cancers." (PMID 36358765, 2022). "Nevertheless, the abnormal expression of SLC2A1 in some cancers still could not be explained, such as LIHC, LUAD, THCA." (PMID 36712872, 2022). "However, there is a lack of systematic and comprehensive studies on the role of SLC2A1 in pan-cancer." (PMID 36712872, 2022). "Several studies have demonstrated that SLC2A1 overexpression is associated with poor clinical outcomes in various types of malignancies, but the precise mechanisms by which SLC2A1 could elevate glucose uptake in cancer cells are not fully understood." (PMID 33735188, 2021). "We first found that YTHDC1 mRNA expression was downregulated in cancer tissues compared with nontumor tissues, and there was a positive association between YTHDC1 and miR-30d and a negative association between YTHDC1 and RUNX1, SLC2A1, HK1." (PMID 34021267, 2021).
cancer (continued). "Since mitochondrial dysfunction after radiation exposure may compromise energy supply and cell function, we focused on the expression of two metabolism-related genes, SLC2A1 and LDHA, which frequent overexpression by cancer cells contribute to increased glycolysis." (PMID 27513864, 2016). "However, two researches in GC focused on SLC2A1 study demonstrated that none of normal gastric epithelium expressed SLC2A1 and nearly 30% carcinoma samples were positive staining of SLC2A1." (PMID 26193257, 2015). "However, a pan-cancer analysis of SLC2A1 has not yet been performed." (PMID 36358765, 2022). "However, no pan-cancer analysis of SLC2A1 had been available thus far." (PMID 36712872, 2022). "Third, our study did not investigate the relationship between SLC2A1 expression and glucose uptake based on PET-CT results in cancer." (PMID 33735188, 2021). "ARG2 expression in cancer cells was not restricted to areas around necrosis or near CAIX-, SLC2A1-, or HIF-1α-expressing cells (data not shown)." (PMID 23424623, 2013). "On the other hand, the time courses of SLC2A1 and CXCR2 indicated disappointing results indicating those markers may not be helpful to monitor the cancer recurrence." (PMID 38514751, 2024). "And from the results of the correlation analysis between the expression level of SLC2A1 and the CNV level of SLC2A1, they were significantly correlated in 19 cancers, including LIHC, KIRC and UCEC, where previous DNA promoter methylation failed to explain the abnormal expression of SLC2A1." (PMID 36712872, 2022). "Notably, the sensitivity of 18FDG-PET for HCC is lower than for other malignant cancers, which suggests 18FDG (−) HCC does not overexpress SLC2A1 and SLC2A3." (PMID 28978124, 2017).
infection (86 papers, 2007 to 2026). The state of being infected such as from the introduction of a foreign agent such as serum, vaccine, antigenic substance or organism. "Specifically, infection induced expression of genes encoding glucose transporter GLUT1 (slc2a1) and monocarboxylate transporter MCT4 (slc16a3)." (PMID 35888991, 2022). "MA10 infection resulted in six additional down-regulated (Cpe, B2m, Pltp, Sparc, Cldn5, Vtn) and four up-regulated DEGs (Slc2a1, Vim, Apod, Acta2), whereas Aβ pathology alone produced one down-regulated (Slc2a1) and three upregulated DEGs (Gfap, Psen1, Clu)." (PMID 41497643, 2025). "Yet, IL-6 levels in the lung were significantly increased in Slc2a1-ΔGr mice at 40 h post-infection." (PMID 41226500, 2025). "We found that both pathways were comparably induced during first and second infection with one notable exception: monocytes switched from upregulating the glucose transporter Slc2a1 in first infection to Slc2a3 in second infection." (PMID 33752799, 2021). "Glucose uptake through the glucose transporter GLUT1 (SLC2A1) increases dramatically after T cell activation in settings of infection and inflammation." (PMID 32814710, 2020). "The mRNA levels of Slc2a1 (Glut1) and Pkm2 were enhanced significantly after infection with wild-type C. rodentium or the mutant strain Δnleb+pNleBc compared to infections with the mutant strain Δnleb and the mutant strain Δnleb+pNleBc-DXD." (PMID 30125331, 2018). "We went on to examine slc2a1 and pkm2 expression levels in mouse livers after infection with the different C. rodentium strains." (PMID 30125331, 2018). "The upregulation of 6-phosphofructo-2-kinase/fructose-2,6-biphosphatase 3 and Phosphoglycerate mutase family member 5 in Colombian and Y-infected cells only; and the downregulation of Solute Carrier Family 2 Member 1 and Phosphofructokinase, liver, B-type in Tulahuen infection." (PMID 38062533, 2023). "Conversely, siRNA knockdown of SLC2A1 significantly inhibited infection." (PMID 37530530, 2023). "As glucose is the substrate of glycolysis, and expression of the genes encoding GLUT-1 (SLC2A1) and GLUT-3 (SLC2A3) were significantly increased after infection, we hypothesized that glucose uptake may also be enhanced." (PMID 35693822, 2022). "Finally, infection resulted in a robust and sustained increase of the glucose transporter (Slc2a1) mRNA levels (more than 9 fold)." (PMID 22928052, 2012). "It was shown that, upon EV-D68 infection, STING co-localised with PI4P as well as glycolytic enzymes, such as HK, PK, and ALDOA, as well as SLC2A1 (GLUT1) in ROs." (PMID 39459875, 2024). "We infected THP-1 cells and sh-slc2a1-treated THP-1 cells that were cultured in RPMI-1640 medium containing 0, 1, or 2 mg/mL glucose during infection." (PMID 34576166, 2021). "When HIF-1α was knocked-down by adding HIF-1α-shRNA-2 lentivirus, the enhancement of expression of SLC2A1 (GLUT1) and PDK1 by infection with the wild-type EPEC E2348/69 strain was diminished." (PMID 30125331, 2018). "Moreover, PX-478 prevented the enhanced expressions of SLC2A1 (GLUT1), PDK1, and PKM2 induced by infection with the mutant EPEC strain ΔnleBE+pNleB." (PMID 30125331, 2018). "The frequency of circulating CD4+Glut1+ T cells and the rs1385129 SLC2A1 SNP may predict the rate of HIV disease progression and CD4+ T cell recovery in untreated and treated infection, respectively." (PMID 29867928, 2018). "Consistently, under hypoxia, the infection of the wild-type EPEC E2348/69 strain induced the expressions of PDK1, PGK1, SLC2A1 (GLUT1), and PKM2, four well-defined HIF-1α targets, but did not induce the expression of SOD2, a well-defined HIF-2α target." (PMID 30125331, 2018).
adenocarcinoma (48 papers, 2003 to 2026). A common cancer characterized by the presence of malignant glandular cells. "Strikingly, high expression of SLC2A1, encoding the glucose transporter GLUT1, and the glycolytic genes GAPDH and PGK1, were associated with strongly reduced OS, particularly in the adenocarcinoma subtype, consistent with the prognostic value of FDG-PET in LuAd." (PMID 31032816, 2019).
metabolic disorders (44 papers, 2015 to 2025). "The glucose transporter type 1 deficiency syndrome (GLUT1DS) was first described by De Vivo in 1991 and consists of an inborn metabolic disease caused by the absence or loss of function of the Glut-1 protein coded in the SLC2A1 gene on chromosome 1." (PMID 33806661, 2021). "In summary, Glut1DS is a treatable neurogenetic metabolic disorder caused by SLC2A1 gene variants." (PMID 41036273, 2025). "Glucose transporter type 1 deficiency syndrome (GLUT1‐DS) is a rare metabolic disorder caused by pathogenic variants in the SLC2A1 gene, which encodes the GLUT1 protein responsible for glucose transport across the blood–brain barrier (BBB) and astrocyte membranes." (PMID 41026139, 2025). "Future studies of the functional role of common polymorphisms in SLC2A1 locus are necessary to define whether glucose metabolic disorder underlies susceptibility." (PMID 39499780, 2024). "Further supporting the altered lipid metabolism observed in metabolic disorders, the solute carrier family 2 member 1 gene (SLC2A1; GLUT1), responsible for glucose transport, was downregulated under the influence of the Geneva kiwifruit cultivar." (PMID 39683393, 2024). "Three had potentially treatable metabolic disorders (SLC2A1, COQ4 and SLC6A8)." (PMID 35979408, 2022).
movement disorder (36 papers, 2011 to 2025). Neurological conditions resulting in abnormal voluntary or involuntary movement, which may impact the speed, fluency, quality and ease of movement. "GLUT1 deficiency syndrome has been characterized as a specific clinical entity encompassing neurodevelopmental impairment, movement disorders, and seizures, and it has been predominately associated with pathogenic SLC2A1 variants." (PMID 36035117, 2022). "In practice, there may be other associated neurological features besides the movement disorder and, especially in the case of SLC2A1-related disease, both the movement disorder and the other associated neurological symptoms may become relatively fixed with time." (PMID 23775978, 2013). "SLC2A1 analysis, seizures, movement disorder, anti-epileptic drugs (AEDS), anthropometry, SE, and laboratory assessment were monitored baseline and at 3, 6, 12, and 24 months after the onset of KDT." (PMID 33806661, 2021). "Expressed in both luminal and abluminal endothelial cells within the blood brain barrier, haploinsufficiency of SLC2A1 causes GLUT1 deficiency syndrome resulting in delayed development, movement disorders, and seizures." (PMID 34414229, 2021).
neurological disorder (26 papers, 2011 to 2026). "Glucose transporter type 1 deficiency syndrome (GLUT1-DS) is a neurological disorder caused by mutations in the SLC2A1 gene." (PMID 38818131, 2024). "The ketogenic diet plays a critical role in managing GLUT1-DS, a neurological disease caused by mutations in the SLC2A1 gene." (PMID 38818131, 2024). "GLUT1 Deficiency Syndrome 1 (GLUT1DS1) is a neurological disorder caused by either heterozygous or homozygous mutations in the Solute Carrier Family 2, Member 1 (SLC2A1) gene." (PMID 34332575, 2021). "Deficiency of glucose transporter SLC2A1 is implicated in several neurological disorders." (PMID 28074849, 2017). "The metabolism and nerve disease–related KEGG pathways were enriched by GSEA analysis of SLC2A1, suggesting its role in the metabolic disturbance of the brain and the neurological disorder in the nonsurvival patients." (PMID 36203605, 2022).
genetic disorder (13 papers, 2011 to 2025). "GLUT1 deficiency syndrome 1 is a genetic disorder which is caused by the mutation in the SLC2A1 gene (locus1p34.2) encoding the GLUT1 glucose transporter protein." (PMID 35053723, 2022). "GLUT1 deficiency is a genetic disorder of impaired glucose transportation across the blood-brain barrier due to mutations in the SLC2A1 gene." (PMID 32775036, 2020). "The Glut1-DS is a rare genetic disease characterized by de novo or inherited mutations (approximately 100 identified) of the SLC2A1 gene." (PMID 31597342, 2019). "Moreover, GLUT1 deficiency syndrome is a genetic disorder caused by autosomal dominant mutations in the SLC2A1 gene, leading to a dysfunctional GLUT1 protein that reduces brain glucose availability." (PMID 40328784, 2025).
neurodevelopmental disorder (8 papers, 2017 to 2026). A behavioral and cognitive disorder with onset during the developmental period that involves impaired or aberrant development of intellectual, motor, or social functions. "GLUT1 deficiency syndrome (G1DS) is a neurodevelopmental disorder that results from haploinsuffiency for GLUT1 due to specific mutations in the SLC2A1 gene." (PMID 38916993, 2024). "Insufficiency of the SLC2A1 gene and the weakness of its translated product, glucose transporter-1 (Glut1) protein, affect glucose uptake, disrupt brain function, and cause neurodevelopmental disorders." (PMID 34163322, 2021). "Haploinsufficiency of the SLC2A1 gene and paucity of its translated product, the glucose transporter-1 (Glut1) protein, disrupt brain function and cause the neurodevelopmental disorder, Glut1 deficiency syndrome (Glut1 DS)." (PMID 28106060, 2017). "Deficiency of the Slc2a1 gene and its translation product (the glucose transporter 1 protein, GLUT1) will impair glucose uptake and affect brain function, thereby leading to neurodevelopmental disorders." (PMID 36497037, 2022).
benign tumors (7 papers, 2008 to 2026). "Meanwhile, patients with PDAC had a higher expression of RUNX1/SLC2A1/ HK1 axis than patients with benign neoplasms." (PMID 34021267, 2021).
bacterial infection (2 papers, 2015 to 2019). "The relative MoDC vs. Mo/MP signature encompasses additional genes that participate in “migration of cells” (p = 10−2.3, with S1PR3, CCL17, and SLC2A1), “bacterial infection” (p = 10−3.2, with CD1B, CD209, and FCGR2B), and “synthesis of nitric oxide” (10−2.5, with PLAU, IL1R2, and NOS2)." (PMID 26150816, 2015).
head and neck tumors (2 papers, 2016 to 2022). "Among all tumors, the frequency of SLC2A1 mutations was highest in gastric, bladder, and head and neck tumors, which is strongly consistent with the results obtained with UALCAN data." (PMID 36712872, 2022). "GLUT1, encoded by SLC2A1, is the predominant transporter overexpressed in tumors, including hepatic, pancreatic, esophageal, brain, renal, lung, cutaneous, colorectal, endometrial, ovarian, cervical, and breast, as well as head and neck tumors." (PMID 27998284, 2016).